CXCL8 (C-X-C motif chemokine ligand 8)
Diseases named in the same sentence as CXCL8 in open-access papers (continued):
Sharing a sentence is not in itself a finding about the gene and the disease.
tumor (continued). "The expression levels of CXCL1, CXCL2, and CXCL8 were significantly elevated, showing a more than threefold increase in over 80% of the analyzed tumor samples." (PMID 38979413, 2024). "CXCL8 is a potent chemokine known to mediate the recruitment and activation of neutrophils at the inflammatory site, as in the tumor microenvironment." (PMID 39335210, 2024). "In a study that examined the cytokine expression profile in tumor tissues of PitNET patients, it was found that all PitNETs express chemokine (C-X-C motif) ligand 8 (CXCL8)." (PMID 38716256, 2024). "DDR1 overexpression promoted tumor growth and increased CXCL8 expression, accompanied by a robust increase in immunosuppressive neutrophils." (PMID 38388466, 2024). "In BCa, CXCL8 is consistently overexpressed and has been correlated with recurrence, progression, higher tumor grade, and poor prognosis." (PMID 39409924, 2024). "C-X-C motif chemokine ligand 8 (CXCL8 or IL-8) is a chemokine that exerts autocrine or paracrine regulation on tumor proliferation, invasion, and migration." (PMID 39568815, 2024). "CXCL8 acts as a strong chemoattractant, potently increasing tumor-promoting behaviors including tumor proliferation, migration, invasion, anoikis suppression, an epithelial to mesenchymal transition (EMT)." (PMID 38385965, 2024). "Tumor volume was positively correlated with levels of CXCL8 (r = 0.18, P = 0.037) and IL6 (r = 0.28, P = 0.004)." (PMID 38965454, 2024). "CXCL8 plays a key role in tumor progression, such as promoting tumor cells proliferation, invasion, and transformation." (PMID 39334887, 2024). "CXCL2 and CXCL8 are two types of chemokine (C-X-C motif) ligand (CXCL), which are generally produced by monocytes and can recruit neutrophils to accumulate in the tumor environment, causing immunosuppression and promoting cancer production and progression." (PMID 38582791, 2024). "The levels of IL-8 in circulation showed a favorable correlation with the expression of the CXCL8 gene inside the tumor and the number of neutrophils and monocytes in the peripheral blood." (PMID 39273452, 2024). "Consistent with these in silico findings, Li A. demonstrated that blocking CXCL8 in the RCC mouse model leads to tumour growth inhibition, suggesting that CXCL8 mediates the process." (PMID 39061159, 2024). "The endpoint of Lineage 4 (Cluster 5) was enriched for the chemokine CXCL8, the major ligand for G-Protein coupled receptor CXCR2 and associated with immune suppression and tumor progression in this context." (PMID 38358352, 2024). "We observed higher expression of CXCL8 in 3D cultures, suggesting culture dimensionality regulates tumor cell hypoxia response and angiogenesis." (PMID 39193365, 2024). "cDC-2 express various markers such as IRF4, CD11b, SIRPα, CLEC10A, and CD1C, and produce IL-1β, IL-6, IL-8, IL-12, TFN-α, CCL3, and CXCL8 to activate anti-tumor T cell responses." (PMID 38533507, 2024). "In functional experiments in a tumour cell-endothelial cell interaction adherence model, adhesion was consistently affected, indicating that CXCL8 also upregulated ICAM1, promoting adhesion between tumour cells and endothelial cells." (PMID 39025845, 2024). "Natural killer (NK) cells can migrate quickly to the tumor site to exert cytotoxic effects on tumors, and some chemokines, including CXCL8, CXCL10 or and CXCL12, can regulate the migration of NK cells." (PMID 38727264, 2024). "Patients’ bronchoalveolar fluid (BALF) and their tumor cells produced CXCL8, the concentration of which correlated with neutrophil numbers and neutrophil elastase activities in BALF." (PMID 38786066, 2024). "The present results revealed that CXCL8 expression was elevated in most surveyed tumor types as compared to corresponding normal tissues." (PMID 38807156, 2024). "Preclinical studies in BM-PCa revealed that CXCL8 promotes in vivo tumor growth and angiogenesis of PC3, an osteolytic PCa cell line derived from a human bone metastasis." (PMID 37025604, 2023).
tumor (continued). "The combination of targeting the CXCL8 pathway and blocking the PD-1 pathway synergistically increased the tumor immune response and inhibited tumor progression." (PMID 37898619, 2023). "The cardinal roles played by S283 were revealed at multiple tumor-promoting levels, including tumor cell proliferation, CXCL8 release and invasion, as well as in vivo." (PMID 37830552, 2023). "One of the mechanisms of neutrophil attraction to the TME is the secretion of CXCL1, CXCL2, CXCL5, and CXCL8 by the malignant cells and the tumor stroma." (PMID 36260158, 2023). "For instance, the hypoxia-induced m6A demethylase alkB homolog 5 (ALKBH5) removes m6A and stimulates tumor macrophage recruitment and tumor immune escape through epigenetic and epitranscriptomic upregulation of CXCL8 in glioblastoma." (PMID 37198402, 2023). "CXCL8 expression was significantly increased in tumours compared to normal and metastatic colon tissue (post hoc Dunn test, p = 6.34 × 10−134 and p = 6.43 × 10−22, respectively)." (PMID 36835258, 2023). "The CXCL8 difference variable (mesenteric-peripheral) also showed a tendency towards a positive correlation with tumour necrosis percentage (beta = 0.144, P = 0.499)." (PMID 37031328, 2023). "In this study, we further explored the expression profile of CXCL8 in the tumor microenvironment and the potential mechanisms of endothelial cell ferroptosis." (PMID 37765018, 2023). "This was manifested by reduced tumor cell growth, CXCL8 release and invasion in siSTAT1-expressing cells compared with siCTRL-expressing cells in WT-PD-L1 cells, not treated or treated with PD-1 (Figure 4C1–C3)." (PMID 37830552, 2023). "In this space, cytokines and chemokines such as TGFβ1, IL-6, IL-6Rα and IL-8 (CXCL8) drive the tumor toward an aggressive mesenchymal state, while IL-10, IL-1RA and TGFβ1 actively suppress expression of immune effector functions." (PMID 37063842, 2023). "CXCL8, a multifunctional proinflammatory chemokine, is increased in both the tumour and tumor-derived microenvironment, where it regulates proliferation, migration, angiogenesis, metastasis, and chemotherapeutic resistance." (PMID 37640804, 2023). "In the present study, PCDH10 overexpression significantly decreased the expression of genes associated with tumor progression and metastasis, including EREG, MMP1, MMP9, TGFB1, RASA4, and CXCL8, in GC cells." (PMID 37147733, 2023). "CXCL8 also recruits medically important stromal cells (MSCs), which suppress the anti-tumor immune function of adaptive T-cell." (PMID 37215082, 2023). "CXCL8 is a multicellular chemokine and is generally produced by monocytes, macrophages, neutrophils, lymphocytes, vascular endothelial cells, and various tumor cells." (PMID 37377954, 2023). "In patients with HCC, CXCL5 serum levels were associated with tumor progression, and levels of CCL20 and CXCL8 with macrovascular invasion." (PMID 36982370, 2023). "On the other hand, other chemokines are associated with the infiltration of tumor sites by myeloid-derived suppressor cells (MDSCs), including CCL2 and CXCL8 (IL-8)." (PMID 37111629, 2023). "As a result of CXCL8, tumor-associated neutrophils (TAN) are recruited, which recruit pro-tumor regulatory T-cell (Tregs) and suppress the anti-tumor immune function of adaptive T-cell." (PMID 37215082, 2023). "Neutrophils are recruited to the tumor (site of injury) through secretion of inflammatory cytokines such as tumor growth factor β (TGFβ), CXCL8 (also known as IL-8), CXCL1, CXCL2 as well as IFNs." (PMID 36910138, 2023). "By analyzing RNA‐sequencing date from TCGA database, we identified that only ETV4, a potential CXCL8 regulator, was highly expressed in tumor tissues compared to normal adjacent tissues (NATs)." (PMID 36670069, 2023). "Overall, activation of the CXCL8/CXCR1/2 axis contributes to a permissive tumor microenvironment for the expansion of neoplastic clones, creating a self-fueling circle in MF." (PMID 37760903, 2023).
tumor (continued). "The TME is enriched in mast cells due to recruitment by chemokines, which promote the EMT of tumor cells via the secretion of CXCL8." (PMID 37905960, 2023). "CXCL8, also known as interleukin-8 (IL8), and its associated pathway CXCL8-CXCR1/2 play an important role in tumour proliferation, invasion, and migration." (PMID 37919768, 2023). "Tumour necrosis percentage positively correlated with peripheral serum levels of CXCL8, a proinflammatory chemokine, and negatively correlated with mesenteric serum levels of CXCL10 and mast cell densities in the invasive margin of the tumour." (PMID 37031328, 2023). "CXCL8 plays a key role in inflammatory responses, promotes the recruitment of neutrophils into tumor tissue, and serves as a proangiogenic factor." (PMID 37174001, 2023). "It is known that CXCL8 regulates tumor behavior through its receptors and downstream signaling pathways." (PMID 37765018, 2023). "CXCL8 is a proinflammatory CXC chemokine, called interleukin-8 (IL-8), involved in tumor angiogenesis to promote tumorigenesis and metastasis." (PMID 36726839, 2023). "A critical function of CXCL8 in tumors is the activation and trafficking of inflammatory mediators, promoting tumor growth and metastasis." (PMID 37940972, 2023). "HNSCC tumor cells produce IL-6, CXCL8, and EGF, which improve the survival and angiogenic potential of endothelial cells through the activation of the STAT3/AKT/ERK signaling pathways." (PMID 38003931, 2023). "As Cohort 2 analyses suggested that peripheral serum CXCL8 levels were positively correlated with tumour necrosis percentage, we sought to validate this." (PMID 37031328, 2023). "This study showed that the statistical parameters of CXCL-8 were higher than the classical tumor markers." (PMID 37046658, 2023). "Tumor-produced CXCL8 can attract both granulocytic as monocytic MDSCs to the tumor microenvironment as shown by in vitro and in vivo models." (PMID 36725964, 2023). "CXCL8 and its receptors are overexpressed in various tumors and correlated with tumor stage and grade 181." (PMID 37497001, 2023). "CXCL8 levels determine the efficacy of sunitinib treatment, which was demonstrated to effectively target MDSCs, suggesting that CXCL8 acts as a potential target in anti-tumor therapy." (PMID 37006306, 2023). "By secreting CCL-2, IL-6, and CXCL8, FAP+ CAF-like cells are able to induce macrophages differentiation into tumor-associated macrophages." (PMID 37166418, 2023). "CXCL8 attracts and stimulates immune cells, but it was also shown to promote angiogenesis and to trigger tumor cell proliferation and progression." (PMID 37174080, 2023). "Expression of chemokine receptors that match ligands secreted by the tumor such as CCL2, CCL22, CXCL16, CX3CL1, CXCL1 and CXCL8 can enable CD8+ T cells to enter the tumor." (PMID 37301772, 2023). "The neutrophils, which represent a pivotal component of the immune response, are intricately recruited to the tumor site through a complex interplay between tumor-derived chemokines and adhesion molecules, such as CXCL8/IL-8 and E-selectin." (PMID 38275384, 2023). "CAA-derived CXCL8 remodeled the tumor immune microenvironment not only by suppressing CD4+ T and CD8+ T immune cell infiltration but also by upregulating CD274 expression in TNBC." (PMID 37898619, 2023). "The role of CXCL8 in bone remodeling and tumor progression makes it ideal for therapeutic targeting." (PMID 37025604, 2023). "Three neutrophil chemokines, CXCL1, CXCL2, and CXCL8 were all found upregulated in the tumor compartment of responders." (PMID 37835599, 2023). "Specifically, we demonstrated that CAAs and CAA-derived CXCL8 played important roles in tumor growth, EMT, metastasis and tumor immunity suppression." (PMID 37898619, 2023). "The involvement of the immune system also creates a positive feedback loop, as the neutrophils in the tumour microenvironment also produce CXCL8, which leads to further neutrophil recruitment." (PMID 37170733, 2023).
tumor (continued). "CXCL8 through CXCR1 can also increase the count of Treg cells in the tumor microenvironment by increasing the expression of TGF-β." (PMID 37686093, 2023). "This neovascularization is essential to supply nutrients and oxygen to the tumor cells and is probably mainly mediated by interaction of CXCL8 with CXCR2-expressing endothelial cells." (PMID 36725964, 2023). "They show that CXCL8 and their cognate receptors, can mediate tumor growth, proliferation, survival, neo angiogenesis, and metastasis of malignant cells, including CRC." (PMID 36854781, 2023). "CXCL8 concentrations were frequently higher in the mesenteric venous blood compared to the peripheral blood, and the positive correlation between tumour necrosis and mesenteric serum CXCL8 (beta = 0.242, P = 0.325) was stronger than with peripheral CXCL8." (PMID 37031328, 2023). "Many researchers have discovered that CD56bright CD16− NK cells that release high levels of cytokines (such as VEGF, placental growth factor, and IL-8/CXCL8) which promote tumor neoangiogenesis exhibit low cytotoxicity in the lung TME." (PMID 37513975, 2023). "CXCL8 was a well-known chemokine involved in tumorigenesis, tumor progression and immune suppression, and CX3CR1 was regarded as a novel cancer targeted therapeutic strategy due to its immune activation capacity." (PMID 37064084, 2023). "One study has demonstrated that the interaction between HCC cells and macrophages promoted tumor cell proliferation, migration and metastasis through the upregulation of CXCL8/miR-17 cluster." (PMID 37393391, 2023). "About CXCL8, our bioinformatics results, and molecular tests on tissue samples indicate an increase in the expression of this gene in tumor and inflammation samples." (PMID 36854781, 2023). "CXC (such as CXCL1, CXCL2, CXCL5, CXCL6, and CXCL8) at the tumor site involve CXCR2+ neutrophils that differentiate into TANs." (PMID 36980182, 2023). "Tumor cells, eosinophils, epithelial cells, fibroblasts, endothelial cells, T cells, macrophages, and neutrophils express CXCL8." (PMID 36831112, 2023). "To summarize, the overexpression of CXCL8 promotes tumor cell proliferation, migration, invasion, EMT, and angiogenesis and accelerates peritoneal metastasis." (PMID 37377954, 2023). "A recent study identified a substantial neutrophil infiltration in the GBM TME, with CXCL8 and IL-8 being the main chemokines attracting neutrophils to the centre of the tumour." (PMID 38136335, 2023). "Neutrophils are attracted to the PDAC TEM by the tumor cells themselves by secreting chemokines (e.g., CXCL8 and CXCL16)." (PMID 37296886, 2023). "Consistently, we further observed ETV4 mRNA expression levels positively correlated with CXCL1 or CXCL8 mRNA expression levels in the tumor tissues." (PMID 36670069, 2023). "IFN-γ activates the RhoGDI2/Rac1/NF-κB pathway in tumor cells to reduce the production of the pro-tumor cytokine CXCL8, promoting tumor apoptosis and reducing CXCR2+ M2 macrophages." (PMID 37275859, 2023). "In the HPV-negative tumor stroma model, the expression level of the neutrophil-specific chemokine CXCL8 was significantly increased, and this mechanism can also recruit more TANs." (PMID 37654657, 2023). "Among them, STAT3 and NF-κB pathways are strongly activated so that IL-6 and CXCL8 act synergistically to promote the proliferation of tumor cells." (PMID 37700840, 2023). "CXCL8 interacts with peritoneal metastases to accelerate tumor progression and leads to a dramatic deterioration of patients." (PMID 37377954, 2023). "CXCL8 is the most representative chemokine produced autocrine or paracrine by tumor cells, endothelial cells and lymphocytes." (PMID 37377954, 2023). "CXCL8 also has a role in neovascularization in the tumor microenvironment, which contributes to tumor growth and metastasis in the tumor microenvironment." (PMID 37138170, 2023).
tumor (continued). "Lymphatic endothelial cells expressed high level of CXCL8/2 via the uptake of tumor cell-derived extracellular vehicles, which induced neutrophil recruitment and NETosis, thereby promoting the formation of premetastatic niche." (PMID 38023616, 2023). "Consistent with the previous experiments, Western blot suggested that the protein expression of CXCL8 is higher in tumor tissues than normal tissues (p < 0.05)." (PMID 36532065, 2022). "The administration of INF-γ inhibited the tumor trafficking of CXCR2+ cells, suppressing the release of tumor-derived CXCL8, ultimately enhancing anti-PD1 efficacy." (PMID 35664746, 2022). "Effect of CXCL8 on tumor angiogenesis has been widely investigated, and CXCL8 has already be defined as a pro-angiogenesis chemokine." (PMID 35372515, 2022). "In conjunction with GM-CSF and M-CSF, tumor-derived lactic acidosis in ovarian cancer was discovered to drive macrophage differentiation into a preinflammatory tumor phenotype (VEGFhigh CXCL8+ IL1β+)." (PMID 36311734, 2022). "More importantly, compared to the classical tumor marker CEA, the serum CXCL8 and its receptor CXCR2 are more valuable on the diagnostic sensitivity, predictive value of negative results, and accuracy." (PMID 35935996, 2022). "CXCL8 is an important cytokine that can modulate proliferation, invasion, and migration of tumor cells and can induce tumor immunosuppression." (PMID 35154316, 2022). "Probably, the effect of CXCL8 on progression is mediated through modulation of the inflammatory response in the microenvironment, activation of tumor stem cells." (PMID 36517518, 2022). "The expression of CXCL8 is inducible under hypoxic conditions in several types of tumor cells, mainly through the cooperative activation of interferon, NF-κB, and activator protein-1 (AP-1)." (PMID 35898871, 2022). "Numerous studies have concentrated on the role of TAMs on CXCL8, which have indicated that TAMs can express or induce tumor cell secreting CXCL8 to contribute to tumor progression." (PMID 35372515, 2022). "In this study, combined scores of stromal CXCL8 and tumour‐infiltrating macrophages (CD68+ cells) or systemic neutrophil counts significantly stratified patient survival." (PMID 35879507, 2022). "As displayed above, components of TME can secret or promote cancer cells to secret CXCL8 which can also subsequently mediate the EMT of tumor cells." (PMID 35372515, 2022). "In recent years, many IHC experiments indicated that the expression of CXCL8 was related to the tumor size, depth of invasion, lymphatic metastasis, and stage of CRC patients." (PMID 35845924, 2022). "In human TC samples, neutrophil density correlated with tumor size, while in vitro studies showed that neutrophils are recruited by TC cells through the release of CXCL8/IL." (PMID 35406748, 2022). "It has been demonstrated that the effect of CXCL8 on facilitating tumor metastasis is mediated by PI3K, AKT, and ERK signaling pathways." (PMID 36612163, 2022). "It was found that CDK1 together with CXCL8 participate in G2M checkpoint, tumor proliferation, EMT, and other pathways." (PMID 36078096, 2022). "In this review, we summarized the current understanding of CXCL8 signaling cascades and recently developed mechanisms of facilitating tumor survival, invasion, and immune suppression." (PMID 35372515, 2022). "CXCR2, the CXC receptor expressed by neutrophils, can bind with its ligand chemokine family (CXCL1, CXCL2, CXCL3, CXCL5, CXCL7, and CXCL8) to recruit neutrophils to the TME and participate in the mobilization of tumour-associated neutrophils." (PMID 36743929, 2022). "Phylogenetically conserved chemokine signaling via CXCL8 increases the exposure of calreticulin on the tumor cell surface, which is critical for dendritic cells (DCs) to recognize and engulf dying tumor cells." (PMID 35656295, 2022). "CAR-NK cells express CXCR1 and are induced to migrate toward cancer cells by secreted CXCL8, exerting tumor- suppressive effects." (PMID 35269786, 2022).